IL5 (interleukin 5)
Diseases named in the same sentence as IL5 in open-access papers (continued):
Sharing a sentence is not in itself a finding about the gene and the disease.
schistosomiasis (continued). "High levels of IL-5 are produced by PBMC and whole blood cell cultures stimulated in vitro with SWA and pre-treatment in vitro SWA specific IL-5 responses are associated with post-treatment SWA-IgE levels, suggesting that IL-5 responsiveness is a key component of human immunity to schistosomiasis." (PMID 23556029, 2013). "The enhanced hepatic expression of IL‐2, IL‐5, IL‐13, or CXCL9 has been described in the context of schistosomiasis progression and generally in cirrhosis." (PMID 40751475, 2025). "The study sought to evaluate cytokine (IL-2, IL-4, IL-5, IL-10, TNF, and IFN-γ) profiles in the serum of children infected with schistosomiasis before and after treatment with praziquantel (PZQ)." (PMID 34239575, 2021). "Furthermore, when IL-5 responses were examined in terms of individuals maintaining long-term antibody protection (above 1 IU/ml) at 8 months, we saw that individuals in the schistosomiasis group that had antibody titers above 1 IU/ml were more likely to produce IL-5 in response to TT stimulation." (PMID 27926921, 2016). "Likewise, IL-5 may participate directly in tissue remodeling and fibrosis in schistosomiasis." (PMID 23320145, 2012). "During murine schistosomiasis, NKT cells could recognize glycolipids presented by CD1d on APCs, inducing the production of type 2 cytokines (IL-4, IL-5, IL-13) and influence the Th1/Th2 balance of the immune response." (PMID 36618421, 2022). "IL13, IL4, IL5, and STAT6 are also involved in regulation of the Th2 response to schistosomiasis." (PMID 33659002, 2021). "From these data we conclude that IL-5 and TNF-α may participate in liver pathology in schistosomiasis." (PMID 23320145, 2012). "These cellular changes were accompanied by a significant reduction in Th2 cytokines IL-4 and IL-5 in Cre+ MGL2+ CD11b+ cDC2 depleted mice, as a proportion of CD4+ T cells, implicating Irf4-dependent dependent cDC2s as critical in promoting type-2 responses during pre-patent schistosomiasis." (PMID 37012228, 2023). "Despite their dominating presence within schistosome infected tissues, the true function of eosinophils in schistosomiasis is not yet known, with eosinophil ablation or IL-5 removal failing to impede granuloma formation or fibrosis, influence hepatocellular damage, or impact Th2 development." (PMID 35958580, 2022). "However, this study also provided evidence for the importance of the Th2 response in acute schistosomiasis, with antigen-specific Th2 (IL-4, IL-5 and IL-13), but not Th1 (IFNγ), CD4+ T cells at week 4 post infection, significantly correlated to acute symptoms." (PMID 33953712, 2021). "In fact, the targeting of identified profibrotic cytokines (IL-5; IL-13) and growth factors (CTGF; TGF-β1 and VEGF) should be pursued in conjunction or as an alternative to current disease control measures to attempt to alleviate the fibrosis process during hepatosplenic schistosomiasis." (PMID 30546364, 2018).
pneumonia (26 papers, 2014 to 2025). An acute, acute and chronic, or chronic inflammation focally or diffusely affecting the lung parenchyma, caused by an infection in one or both of the lungs (by bacteria, viruses, fungi, or mycoplasma.). "Important for therapeutic implications, and more central to our findings here, increased expression of IL-13 and IL-5 in lungs of CF patients is associated with occurrence of acute pneumonia exacerbations." (PMID 28680858, 2017). "Appropriate selection of COPD patients with an eosinophilic pattern permits to add inhaled corticosteroids to bronchodilators in the right patients limiting the risk of pneumonia and to select potential patients to be treated with new monoclonal antibodies against IL-5." (PMID 31291952, 2019). "Patients with varying pneumonia severity also showed differences, with higher IL-5 levels in convalescent patients with mild disease, aligning with reports that cytokine dysregulation varies widely among patients." (PMID 40557167, 2025). "Patients with severe pneumonia and high clinical pulmonary infection scores presented higher levels of IL-4 and IL-5 in serum than those with low scores (P < 0.01)." (PMID 24977240, 2014). "Also, patients with severe pneumonia had significantly higher serum levels of IL-4, IL-5, and IL-13 than those with mild pneumonia, indicative of the role of influenza virus infection in airway type 2 inflammation." (PMID 40083723, 2025). "In the present study, the cytokines, TNF, IL-1β, IL-6, IL-8, IL-12p70, IFN-γ, IL-17A, IL-10 and IL-5, were detected in the serum of children with pneumonia and severe pneumonia at hospital admission, and IL-6 was the only cytokine associated with disease severity." (PMID 27905908, 2016). "Relative to controls, cytokines that were significantly elevated in the pneumonia cohort at 24 and/or 48 h after inoculation (evolution phase) were IL‐1β, IL‐6, IL‐15, IL‐16, IL‐17a, IP‐10, MCP‐1, MIP‐1β, and TARC; IL‐5 was significantly elevated at 168 h (resolution phase)." (PMID 40947770, 2025). "In human, among 34 children aged 2–11 years infected with H1N1 influenza A virus, 21 patients with pneumonia had higher serum levels of IFN-γ and IL-5 than patients without pneumonia." (PMID 40083723, 2025). "Compared to pH1N1 patients without pneumonia, those who developed acute pneumonia due to pH1N1 exhibited significantly elevated levels of Th2 cytokines (IL-4, IL-5, and IL-13) in their serum." (PMID 40529241, 2025). "IL-6 and IL-5 in the migraine group were statistically different from those in the pneumonia group without headache." (PMID 38356891, 2024). "Here, we analyzed the levels of EOS, IgE, IL-4, IL-5 and INF-γ in children with pneumonia." (PMID 39764167, 2024). "We found that high levels of IL-6, IFN-γ, and IL-2 and low levels of IL-5, IL-25, IL-17A, and IL-22 were found in the severe pneumonia group compared to the nonsevere pneumonia group." (PMID 34692846, 2021). "Serum IL-6, sCD40L, IL-5 and IL-2 further rose in time point B in patients who developed severe pneumonia, while no such change was seen in patients with DHF." (PMID 33199778, 2020). "Our data showed that neonatal S. pneumoniae pneumonia can increase the infiltration of inflammatory cells, both in the lung tissues and in the BALF, along with releasing higher levels of the pro-inflammatory cytokines (IL-4, IL-5, IL-13, and IL-17A)." (PMID 30723734, 2019). "In addition, the levels of IL-4, IL-5, IL-13, and IL-17A in BALF were also significantly higher in the pneumonia group." (PMID 30723734, 2019). "Another study found higher concentrations of IL-10 and IL-5 in H1N1-infected patients with pneumonia compared to H1N1-infected patients without pneumonia." (PMID 26407163, 2015). "Despite we do not find any association between IL-5 and the absolute eosinophil count of our patients (data not shown), our results suggest that the Type 2 immune response is involved and may be aggravated by SARS-CoV-2-induced pneumonia." (PMID 37207201, 2023).
atopic asthma (25 papers, 2010 to 2025). An asthma that is characterized by symptoms that are triggered by an allergic reaction caused by inhaled allergens such as dust mite allergen, pet dander, pollen and mold. "Studies have associated SNPs in the IL5 gene with atopic asthma, increased IL5 mRNA expression, and decreased lung function and eosinophil count." (PMID 39125709, 2024). "On the other hand, severe eosinophilic atopic asthma and allergic CRSwNP share common pathogenic mechanisms including the key roles played by IgE and IL-5-dependent airway eosinophilia." (PMID 34944638, 2021). "Whereas an increased IL-5/IL-10 ratio has been reported in patients with atopic asthma, atopy itself is associated with a modest rise in the risk of dementia, in support of an inflammatory component in the etiology of neurodegenerative dementia." (PMID 24655894, 2014). "Indeed, anti-IL5 antibody treatment inhibits the induction of airway subepithelial fibrosis in a murine model of atopic asthma, suggesting a pathogenic role for this cytokine in lung pathology." (PMID 32310998, 2020). "It is now generally accepted that Th2 cells and Th17 cells significantly contributed to atopic asthma, hence we detected Th2-derived cytokines—IL-4, IL-5, IL-13, and Th17-derived cytokines—IL-17A in BALF." (PMID 33013383, 2020). "Both IL-5 and IL-13 are effector molecules essential to type 2-inflammation, especially in atopic asthma and viral respiratory tract infections." (PMID 29768624, 2018). "Japanese authors in their study concluded that the production of IL-5 is higher in asthmatics then in healthy subjects as follows: atopic asthma – 37.6 ± 7.1 pg/ml; non-atopic asthma – 25.7 ± 5.5 pg/ml and halthy subjects – 3.0 ± 0.4 pg/ml." (PMID 27275299, 2015). "The consistent differentiation and presence of eosinophils due to IL-5 might lead to chronic AD and atopic asthma." (PMID 34070943, 2021). "In addition, the frequency of circulation Th2 cells that produce both IL-17A and classical Th2 cytokines (IL-4, IL-5, and IL-13) is higher in patients with atopic asthma than healthy controls." (PMID 34344357, 2021). "Recent evidence shows indeed that, in atopic asthma, the production of FeNO is stimulated by proinflammatory T2-cytokines, other than IL-5, such as IL-4 and IL-13, making NO a biomarker of T2-driven inflammation, which is not susceptible to the action of the anti-IL5 mAbs." (PMID 30498762, 2018). "Although the immunopathological features of atopic asthma are well characterized as an eosinophilic bronchitis in the airways, with the inflammatory process governed by Th2 cytokines, such as IL-4, IL-5 and IL-13, the immunological and cellular profiles of non-atopic asthma are not well known." (PMID 23253516, 2012). "Eugenol, also detected in Bronchom has also been evaluated for its in-vivo efficacy in a murine model of atopic asthma induced by ovalbumin, wherein it suppressed AHR, eosinophilic influx in BALF and the lungs as well as the release of IL-4 and IL-5." (PMID 39129025, 2024). "In line with the increase of CCR4+ T cells in patients, T cells from atopic asthma patients secreted more of IL-5 and IL-13 than T cells from non-asthmatic control subjects." (PMID 29507584, 2018). "Atopic asthma patients with increased TNC basement membrane thickness were also found to have higher eosinophils, T-lymphocytes, macrophages, IL-4+ cells, and anti-IL-5 treatment reduced deposition of TNC in the bronchial subepithelial basement membrane of mild atopic asthmatics." (PMID 36829478, 2023).
diabetes (25 papers, 2012 to 2025). "In this study, we examined the correlation between IL-5 and cognitive dysfunction in diabetes and explored the potential diagnostic value of IL-5 in diabetic cognitive impairment." (PMID 39347908, 2025). "Although IL-5 is both associated with cognitive dysfunction and diabetes (including diabetic complications), the relationship between IL-5 and MCI in T2DM patients is still unclear." (PMID 39347908, 2025). "Here, we endeavor to scrutinize the potential contribution of interleukin-5 (IL-5) towards mild cognitive impairment (MCI), and to assess its diagnostic value for MCI in patients with type 2 diabetes mellitus (T2DM)." (PMID 39347908, 2025). "The number of studies investigating IL-5 levels in the blood of patients with diabetes, including prediabetes and metabolic syndrome, is limited and the results are contradictory." (PMID 39201047, 2024). "The high-glucose environment of diabetes significantly increases the cytokines, such as interleukin 4(IL-4), interleukin 5(IL-5), interleukin 6(IL-6), interleukin 13(IL-13), and tumor necrosis factorα (TNF-α)." (PMID 35669482, 2022). "Certain studies have found IL-5 to be reduced in diabetes, while others have found IL-5 plasma levels to be correlated with glycosylated hemoglobin in diabetic patients." (PMID 31992349, 2020). "The present study investigates the association of IL-5 with inflammation and its neuroprotective effects on the neuroinflammation within the hippocampus of murine subjects, with and without diabetes." (PMID 39347908, 2025). "In the periodontally healthy sites, the concentrations of IL-4, IL-5, IL-7, and IL-13 were decreased in the diabetes group compared to those in the control group; TGF-β concentrations were also decreased in the control group versus those in the rest of the groups (p < 0.05)." (PMID 37835794, 2023). "Furthermore, generation of IL-5-producing GAD65-specific CD4+ T cells was shown to protect NOD mice from diabetes development." (PMID 23390544, 2013). "Additionally, levels of IL-5 elevated in humans and animals with diabetes." (PMID 39347908, 2025). "Indeed, IL-5 is also associated with cognitive function in both children and adults, irrespective of diabetes status." (PMID 39347908, 2025). "Diabetes related biomarkers: GIP, GLP-1, leptin, glucagon and inflammatory cytokines: IL-4, IL-5, IL-10, IL-12, IFN-g and TNF-α were significantly affected by HFB diet compared to HF diet." (PMID 34441468, 2021). "Diabetes related biomarkers, gastric inhibitory polypeptide (GIP), leptin, glucagon, and inflammatory cytokines interleukin 4 (IL-4) and IL-5, 10 and 12, IFN-g and TNF-α were significantly affected by HFB diet." (PMID 34441468, 2021). "Weobserved a statistically significant decrease of MCP-1/CCL2, GM-CSF, IL-5,IL-6, and IFN-γ in the saliva of patients with chronic periodontitisassociated with type 2 diabetes mellitus in comparison with patients withchronic periodontitis only." (PMID 31993238, 2019). "A significant reduction in the levels of IL-5, CCL-3/MIP-1α, and CCL-11/eotaxin was observed in the lungs of allergen-challenged mice under condition of diabetes." (PMID 29849493, 2018). "Additional models controlling for gender, pulmonary source of infection, and diabetes were built for EGF, VEGF, IL4, IL5, and IL13." (PMID 26064774, 2015). "Concentration of IL-5 has been reported higher in DR patients compared to patients suffering from diabetes without retinopathy and among different stages of DR IL-5 has been found higher in PDR than NPDR24." (PMID 30410092, 2018). "In animals, up-regulated IL-5 mRNA and protein levels were detected by RNA-seq and (or) verified experiments in the hippocampus of diabetic db/db mice with cognitive decline, compared to those of db/m mice without diabetes." (PMID 39347908, 2025).
diabetes (continued). "A study of the cytokine response demonstrated that in the mice with developed alloxan-induced diabetes, the concentrations of all measured cytokines in the plasma increased on the 10th day after the administration of alloxan, with the most marked increase observed in TNF-α and IL-5." (PMID 32908936, 2020). "The induction of diabetes mellitus leads to the initiation of the inflammatory process and the release of pro-inflammatory cytokines such as IL-2 and TNF-α and does not produce any change in the levels of IL-4, IL-5, and INF-ɣ." (PMID 37842429, 2023). "This comparison demonstrated that diabetes may lead to an increase in the levels of IL-2 and TNF-α without altering the levels of IL-4, IL-5, and INF-ɣ (p>0.05)." (PMID 37842429, 2023).
eosinophilic granulomatosis with polyangiitis (24 papers, 2017 to 2026). Eosinophilic granulomatosis with polyangiitis (EGPA), previously known as Churg-Strauss syndrome, is a systemic vasculitis of small-to medium vessels, characterized by asthma, transient pulmonary infiltrates, and hypereosinophilia. "Therapies targeting interleukins such as IL-6 (e.g., tocilizumab) and IL-5 (e.g., mepolizumab) have been explored, particularly in eosinophilic granulomatosis with polyangiitis (EGPA), a subset of AAV." (PMID 40507398, 2025). "Eosinophilic granulomatosis with polyangiitis, previously known as Churg–Strauss syndrome, is characterized by increased blood level of IL-5 and eosinophilia in peripheral blood and affected tissues." (PMID 28791287, 2017). "Blockage of the IL-5/IL-5R axis is promising and has been well studied in recent years within numerous diseases such as eosinophilic asthma, eosinophilic granulomatosis with polyangiitis (EGPA), chronic rhinosinusitis with polyposis, hypereosinophilic syndrome, and eosinophilic esophagitis." (PMID 36035809, 2022). "Mepolizumab, targeting interleukin-5 (IL-5), has been evaluated in eosinophilic granulomatosis with polyangiitis (EGPA), a subset of AAV." (PMID 40507398, 2025). "The latest evidence of efficacy and safety of an interleukin-5 inhibitor, mepolizumab, has improved the therapy of refractory or recurrent eosinophilic granulomatosis with polyangiitis (EGPA)." (PMID 35155037, 2022). "Mepolizumab (MPZ), an anti-interleukin-5 antibody, is effective for the treatment of eosinophilic granulomatosis with polyangiitis (EGPA)." (PMID 33726827, 2021). "In some cases, eosinophilic granulomatosis with polyangiitis (EGPA) may be masked by prior treatment, such as corticosteroids or anti-IL5 treatment." (PMID 39860330, 2025). "In eosinophilic granulomatosis with polyangiitis (EGPA), upper and lower airway manifestations—including chronic rhinosinusitis and eosinophilic otitis media (EOM)—can persist or relapse despite high-dose anti–IL-5 therapy." (PMID 41210307, 2025). "Even in eosinophilic granulomatosis with polyangiitis (EGPA), not all manifestations of eosinophilic inflammation respond equally to anti–interleukin-5 (IL-5) therapy." (PMID 41210307, 2025).